RSL1D1 (ribosomal L1 domain containing 1)
Description:
Regulates cellular senescence through inhibition of PTEN translation. Acts as a pro-apoptotic regulator in response to DNA damage.
Synonyms: CSIG; PBK1; L12; Cic1; DKFZP564M182; UTP30
Tractability: Small molecule: a structure with a bound ligand is known. PROTAC: UniProt records ubiquitination sites on it; ubiquitination databases record sites on it; its protein half-life has been measured.
Target class: Other nuclear protein
Gene: Protein-coding gene on chromosome 16 (11,833,850 to 11,851,586, reverse strand). Ensembl gene ENSG00000171490.
Subcellular location: Nucleus, nucleolus
Subcellular location (Human Protein Atlas): Mitotic chromosome; Nucleoli rim; Primary cilium; Vesicles
Gene Ontology:
Molecular function: cadherin binding; mRNA 3'-UTR binding; mRNA 5'-UTR binding; protein binding; RNA binding
Biological process: osteoblast differentiation; regulation of apoptotic process; regulation of cellular senescence; regulation of protein localization
Cellular component: membrane; nucleolus
Genetic constraint (gnomAD): Loss-of-function variants: 32 observed, 40.45 expected, observed/expected ratio (o/e) 0.79, 90% interval 0.6 to 1.06. The synonymous counts are far from expectation, so gnomAD's model fits this gene poorly and the ratio says little. Missense variants: 706 observed, 546.19 expected, observed/expected ratio (o/e) 1.29, 90% interval 1.21 to 1.38. Synonymous variants: 252 observed, 201.58 expected, observed/expected ratio (o/e) 1.25, 90% interval 1.13 to 1.39.
Homologues: Orthologues: chimpanzee RSL1D1 (99% identical), macaque RSL1D1 (93% identical), dog RSL1D1 (68% identical), pig RSL1D1 (65% identical), rabbit RSL1D1 (64% identical), guinea pig RSL1D1 (63% identical), mouse Rsl1d1 (53% identical), rat Rsl1d1 (40% identical), zebrafish rsl1d1 (28% identical), Drosophila melanogaster RpL7A (11% identical), Caenorhabditis elegans rpl-7A (10% identical). Paralogues in human: RPL7A (13% identical), RPL10A (9% identical), NHP2 (4% identical).
Diseases named in the same sentence as RSL1D1 in open-access papers:
RSL1D1 is named in the same sentence as 13 diseases in open-access papers, as found by Europe PMC text mining. Sharing a sentence is not in itself a finding about the gene and the disease. The quoted sentences say what the papers report.
colorectal cancer (5 papers, 2021 to 2025). A primary or metastatic malignant neoplasm that affects the colon or rectum. "RSL1D1 inhibits cellular senescence—a state of cell cycle arrest for aged cells—in various cancers, such as colorectal cancer." (PMID 40429796, 2025). "RSL1D1 (ribosomal L1 domain containing 1), a member of the universal ribosomal protein uL1 family, was suggested to be a new candidate target for colorectal cancer (CRC)." (PMID 35013134, 2022). "Here, we also demonstrated that RSL1D1 promoted the progression of colorectal cancer by suppressing autophagy." (PMID 35013134, 2022). "Mechanistically, RSL1D1 promoted the progression of colorectal cancer by suppressing autophagy." (PMID 35013134, 2022).
hepatocellular carcinoma (4 papers, 2015 to 2022). A malignant tumor that arises from hepatocytes. "Accordingly, several studies revealed that RSL1D1 could also promote the progression of other cancers, including liver carcinoma and prostate cancer." (PMID 35013134, 2022).
breast carcinoma (3 papers, 2020 to 2023). "The top predicted pan-cancer regulators including RSL1D1, DDX21 and SMC2, were experimentally validated in lung, colon, breast cancer and fetal kidney cells." (PMID 38102665, 2023). "CALCR (coding calcitonin receptor) has similar gene expression patterns to MAD2L1 and RSL1D1 in tamoxifen-resistant MCF7 cells; the expression of these genes was all correlated with worse RFS in ER-positive/HER2-negative breast cancer patients who had undergone endocrine therapies only." (PMID 33133141, 2020). "We further identified several novel pan-cancer splice variants (chr16:11851406 with chr16:11820297, chr16:11821755 and chr16:11828391, each present across up to eight different cancers) in RSL1D1 and its neighboring BCAR4, a long non-coding RNA known to promote breast cancer progression." (PMID 34316681, 2020). "Therefore, MAD2L1, RSL1D1, and CALCR might be promising candidates for further research in endocrine therapy-resistant breast cancer as potential therapeutic targets or prognostic markers." (PMID 33133141, 2020).
prostate carcinoma (3 papers, 2020 to 2022). A carcinoma that arises from epithelial cells of the prostate gland. "Recently, a high expression of Ribosomal L1 domain containing 1 (RSL1D1), a nuclear protein involved in senescence and regulation of cellular apoptosis, has been associated with poor prognosis of prostate cancer." (PMID 34155232, 2021). "RSL1D1 (ribosomal L1 domain containing 1) is a nucleolar protein that has been demonstrated to delay cellular senescence and serve as an independent prognostic factor in prostate cancer." (PMID 33133141, 2020).
colon cancer (1 paper, 2024). "Knockdown of RSL1D1 promoted autophagy, invasion and migration of colon cancer cells, while overexpression of RSL1D1 inhibited autophagy in colon cancer cells." (PMID 39684863, 2024).
non-small cell lung carcinoma (1 paper, 2021). A group of at least three distinct histological types of lung cancer, including non-small cell squamous cell carcinoma, adenocarcinoma, and large cell carcinoma. "Since RSL1D1, as a nucleolus-localized protein, is released to the nucleoplasm of H1299 non-small cell lung cancer cells upon nucleolar stress, an IF assay was performed to address whether this nucleolus-nucleoplasm translocation of RSL1D1 occurs in HCT116 CRC cells." (PMID 34362424, 2021).
tumor (9 papers, 2015 to 2025). "Cellular senescence-inhibited gene (CSIG), also named as ribosomal_L1 domain-containing 1 (RSL1D1), is implicated in various processes including cell cycle regulation, cellular senescence, apoptosis, and tumor metastasis." (PMID 26029164, 2015). "The subcutaneous tumor model showed that knockdown of RSL1D1 inhibited the tumor growth of SW480 cells in vivo." (PMID 35013134, 2022). "Collectively, our results demonstrated that RSL1D1 overexpression promoted the growth and metastasis of CRC cells in vitro and in vivo, strongly indicating that RSL1D1 functions as a tumor promoter in CRC." (PMID 35013134, 2022). "We further analyzed the mRNA expression of RSL1D1 in CRC samples using GEPIA public data, and the results showed that the expression of RSL1D1 mRNA in CRC tumor tissues was higher than that in normal intestinal tissues (P < 0.01)." (PMID 35013134, 2022). "Tumor samples from 231 CRC patients were used to analyze the correlation between RSL1D1 expression and the clinicopathological characteristics or prognosis of CRC patients by immunohistochemical (IHC) staining." (PMID 35013134, 2022). "The therapeutic efficacy of RSL1D1 silencing on tumor growth was evaluated in HCT116 tumor-bearing nude mice." (PMID 34362424, 2021). "Our findings suggested that RSL1D1 may be a tumor-promoting gene in CRC." (PMID 35013134, 2022). "More importantly, these findings suggest that “extra-nucleolar” RSL1D1 and PDCD11 should be potential tumor markers in CRC theranostics." (PMID 38062028, 2023). "In summary, our study uncovered the key role of the RSL1D1/RAN/STAT3 regulatory axis in autophagy and tumor progression in CRC, highlighting a new target for preventing and treating CRC." (PMID 35013134, 2022). "Taken together, our study uncovered the key role of the RSL1D1/RAN/STAT3 regulatory axis in autophagy and tumor progression in CRC, providing a new candidate target for CRC treatment." (PMID 35013134, 2022). "Functionally, RSL1D1 overexpression significantly promoted the proliferation and invasion of CRC cells in vitro and tumor growth and metastasis of CRC cells in vivo." (PMID 35013134, 2022). "In general, our results indicated that RSL1D1 was highly expressed in tumor samples from patients with CRC and that high expression of RSL1D1 was correlated with poor prognosis." (PMID 35013134, 2022). "Using a suppressive subtractive hybridization system, we previously identified a CSIG (also known as RSL1D1), which is involved in important processes including senescence, cell cycle regulation, stress response, and tumor metastasis." (PMID 26029164, 2015).
cancer (8 papers, 2017 to 2025). A tumor composed of atypical neoplastic, often pleomorphic cells that invade other tissues. "This axis is turned in favor of cancer cells by ribosomal L1 domain containing 1 (RSL1D1), which competitively binds to SIRT7 and inhibits RAN deacetylation." (PMID 37676263, 2024). "The contrary regulatory mechanism is probably attributed to the different subnuclear localization of RSL1D1 in different types of cancer cells." (PMID 34362424, 2021). "As an inhibitor of cellular senescence, RSL1D1 is highly expressed in liver, prostate, and breast cancers, suggesting that it may be closely related to the pathogenesis and progression of many cancers." (PMID 35013134, 2022). "The upregulation of FOXO3a contributed to G2/M arrest in RSL1D1-downregulated HCT116p53−/− cells, thereby inhibiting cell proliferation, which is consistent with the current opinion that FOXO3a activation induces G2/M arrest in various cancer cells." (PMID 34362424, 2021). "However, the role of RSL1D1 in cancer, including CRC, remains largely elusive." (PMID 35013134, 2022).
RSL1D1 also shares sentences with these, for which no sentence is quoted: infection (2 papers); colorectal tumors (1); liver cancer (1); malignant pheochromocytomas (1); osteosarcoma (1).